PTK6 (protein tyrosine kinase 6)
Diseases named in the same sentence as PTK6 in open-access papers (continued):
Sharing a sentence is not in itself a finding about the gene and the disease.
prostate adenocarcinoma (2 papers, 2011 to 2017). "Using a transgenic mouse model, we found that Ptk6 null mice are more resistant to developing invasive prostate adenocarcinoma following prostate-specific Pten deletion." (PMID 29142193, 2017). "PTK6 is also primarily cytoplasmic in the PC3 prostate adenocarcinoma cell line." (PMID 21479203, 2011). "Expression of PTK6 and ALT-PTK6 was also analyzed in primary cultures of normal epithelial cells derived from fourteen prostates (peripheral zone) and epithelial cells from fifteen prostate adenocarcinomas using PCR." (PMID 21479203, 2011).
psoriasis (2 papers, 2010 to 2011). An autoimmune condition characterized by red, well-delineated plaques with silvery scales that are usually on the extensor surfaces and scalp. "The EGF-family ligand TGF-α (Tgfa) and the kinase Ptk6, which are also increased in both psoriasis and PPARδ transgenic mice, were elevated in SKO mice as well." (PMID 21573029, 2011). "Second, PTK6 kinase, which also phosphorylates STAT3, is the most highly upregulated kinase in psoriasis and PPARβ/δ mice." (PMID 20300524, 2010).
atrial septal defect (1 paper, 2023). Interauricular communication is a congenital malformation characterized by a communication between the atrial chambers of the heart. "KHDRBS2 is an important member of PTK6 signaling and is associated with atrial septal defect." (PMID 37055782, 2023).
Co-infection (1 paper, 2015). "Co-infection of Bim shRNA (with either of two independent vectors) rescued PTK6 shRNA-expressing cells from apoptosis, as assessed by levels of cleaved PARP and number of Annexin V-positive cells." (PMID 26084280, 2015).
colon adenocarcinoma (1 paper, 2025). "Conversely, PTK6 expression levels are significantly lower in colon adenocarcinoma (COAD), glioblastoma multiforme (GBM), head and neck squamous cell carcinoma (HNSC), and kidney chromophobe (KICH) when compared to normal tissues." (PMID 40809015, 2025).
colorectal adenocarcinoma (1 paper, 2016). The most common type of colorectal carcinoma. "In the SW620 colorectal adenocarcinoma cell line, targeting nuclear PTK6 negatively regulated endogenous β-catenin/T cell factor (TCF) transcriptional activity, whereas targeting membrane PTK6 enhanced β-catenin/TCF-regulated transcription." (PMID 27311570, 2016).
Crohn disease (1 paper, 2024). A gastrointestinal disorder characterized by chronic inflammation involving all layers of the intestinal wall, noncaseating granulomas affecting the intestinal wall and regional lymph nodes, and transmural fibrosis. "In patients with Crohn’s disease, PTK6 is upregulated in tuft cells in noninflamed regions of intestine." (PMID 39461944, 2024).
cutaneous melanoma (1 paper, 2025). A primary melanoma arising from atypical melanocytes in the skin. "Therefore, although the overall mutation rate of PTK6 is low in cutaneous melanoma, the integrity of its key domains and expression regulation still have important impacts on tumor biological behavior." (PMID 40809015, 2025). "This reveals that PTK6 enzymatic activity is involved in these biological processes, providing important evidence for understanding the role of PTK6 in cutaneous melanoma and its potential feasibility as a therapeutic target." (PMID 40809015, 2025). "This study confirms PTK6’s involvement in cutaneous melanoma pathogenesis, highlighting its crucial role and therapeutic promise." (PMID 40809015, 2025). "To determine the relationship between elevated PTK6 expression levels and the progression of cutaneous melanoma, we designed the following experiments." (PMID 40809015, 2025). "In this study, we conducted an in-depth analysis utilizing data from The Cancer Genome Atlas (TCGA) and employing statistical and bioinformatics methodologies to further explore the involvement of PTK6 in the pathogenesis and prognosis of skin cutaneous melanoma (SKCM)." (PMID 40809015, 2025). "When analyzing large-sample databases such as TCGA, we found that the somatic mutation frequency of the PTK6 gene was relatively low in cutaneous melanoma, and no obvious high-frequency mutation sites were observed." (PMID 40809015, 2025). "However, PTK6’s role in cutaneous melanoma pathogenesis remains uninvestigated." (PMID 40809015, 2025).
ductal carcinomas (1 paper, 2014). "Unlike in the ductal carcinomas, PTK6 was nuclear in the LCIS that we examined." (PMID 25153721, 2014).
intestinal infection (1 paper, 2024). "We examined publicly available datasets from different intestinal infection models for Ptk6 expression." (PMID 39461944, 2024).
invasive lobular carcinoma (1 paper, 2014). "Increased PTK6 mRNA expression relative to normal tissue was previously reported to be significant independent of tumor subtype in invasive ductal and invasive lobular carcinoma in the TCGA breast dataset." (PMID 25153721, 2014).
papillary thyroid cancers (1 paper, 2015). "Meanwhile, in papillary thyroid cancers, miR-17 is downregulated and negatively associated with clinical staging, whereas PTK6 is upregulated and positively associated with clinical stages." (PMID 25748447, 2015). "To validate the role of PTK6 and miR-17 in papillary thyroid cancers (PTC), we analyzed PTK6 and miR-17 expression in 162 pairs of clinical PTC and 162 adjacent nontumorous tissues (ANT)." (PMID 25748447, 2015). "In this study, we sought to determine the role of S1P in PTK6, miR-17 and ERK1/2 expression and to determine whether S1P regulates the migration of papillary thyroid cancer cells via a miR-17 /PTK6/ ERK1/2 signal." (PMID 25748447, 2015). "Although several functions of PTK6 have been described, a role for PTK6 in papillary thyroid cancer has not been established." (PMID 25748447, 2015).
prostate (1 paper, 2017). "Here we demonstrate that disruption of Ptk6 in the PB-Cre4, Ptenflox/flox model impairs prostate tumorigenesis." (PMID 29142193, 2017).
rectal tumors (1 paper, 2023). "Colon and rectal tumors also express higher levels of PTK6 than the normal intestine suggesting a potential role in tumorigenesis." (PMID 37509364, 2023).
Salmonella Infections (1 paper, 2024). Infections with bacteria of the genus SALMONELLA. "In a single cell (sc) RNA-seq study, we found Ptk6 is significantly upregulated in small intestinal tissue at 10 days post-Hb infection (Hb D10) and 2 days after Salmonella infection." (PMID 39461944, 2024).
thyroid follicular carcinoma (1 paper, 2015). "Together, these results demonstrate that miR-17 suppresses S1P-induced follicular thyroid cancer cell migration by PTK6 and ERK1/2." (PMID 25748447, 2015). "We next examined the functional relevance of the miR-17/PTK6 interaction in follicular thyroid cancer cells." (PMID 25748447, 2015). "In this study, we showed that S1P induced PTK6 mRNA and protein expression in two thyroid follicular cancer cell lines (ML-1 and FTC-133)." (PMID 25748447, 2015). "Further, studies showed that miR-17 inhibits S1P induced migration of thyroid follicular carcinoma cells by targeting PTK6 and inhibiting ERK1/2 signaling." (PMID 25748447, 2015). "We also showed that S1P increased PTK6 mRNA and protein expression in a dose- and time-dependent manner in follicular thyroid cancer cells (FTC-133 cells)." (PMID 25748447, 2015). "All of these results demonstrate that PTK6 and ERK1/2 signaling are involved in the migration of follicular thyroid cancer cells in response to S1P stimulation." (PMID 25748447, 2015). "In this study we showed that S1P induces PTK6 expression and induces PTK6 activated ERK1/2 signaling, resulting in thyroid follicular carcinoma cell migration." (PMID 25748447, 2015).
urethral carcinomas (1 paper, 2017). "More than 25% of PB-Cre4, Ptenflox/flox mice (3/11) developed urethral carcinomas, in contrast with 0/11 PB-Cre4, Ptenflox/flox, Ptk6−/− mice." (PMID 29142193, 2017). "Interestingly, disruption of Ptk6 also impaired development of urethral carcinomas in the PB-Cre4, Ptenflox/flox mice." (PMID 29142193, 2017).
cancer (71 papers, 2006 to 2026). A tumor composed of atypical neoplastic, often pleomorphic cells that invade other tissues. "Prognostic analysis using the Cox model showed that elevated PTK6 expression is associated with decreased survival in several cancers, particularly KIRC, SKCM, and PAAD (p<.05)." (PMID 40809015, 2025). "While PTK6 is mainly associated with cancer, it is also expressed in EBV-transformed B cells, suggesting a possible indirect link between this antigen and MS disease." (PMID 39669579, 2024). "Antagonism of GRK6, a member of the G-coupled receptor kinase family associated with insulin secretion and T2D susceptibility, and PTK6, an oncogenic kinase studied in the context of cancer, led to the inhibition of T cell activation in the nM to uM range." (PMID 39302339, 2024). "In these cancers, oncogenic functions of PTK6 have been associated with its activation at the plasma membrane." (PMID 36228719, 2022). "PTK6 upregulation has been identified in multiple cancer types and is associated with poor patient prognosis." (PMID 35562900, 2022). "In most situations, increased PTK6 mRNA levels contribute to cancer cell migration, invasion, and metastases, and are associated with decreased survival, same with our study result." (PMID 36158685, 2022). "Overexpression of PTK6 is found in late tumor stages and is associated with poor patient prognosis in multiple cancer types including HCC6–8." (PMID 31844057, 2019). "PTK6 has been implicated in a variety of tissues and cancers and is related to the regulation of different signaling pathways." (PMID 27311570, 2016). "We also found other cancer-associated signaling pathways enriched, such as “signaling by PTK6” (Reactome pathway, P = 5.26e-05) and “ErbB signaling pathway” (KEGG pathway, P = 1.26e-04) among PPM1A neighbors." (PMID 27333808, 2016). "Several downstream effector molecules associated with PTK6 have previously been identified in other cancers." (PMID 24788754, 2014). "Despite PTK6’s association with various cancers, its specific role and prognostic significance in CM remain unclear." (PMID 40809015, 2025). "The underlying mechanism by which PTK6 works in cancer biology is gradually being revealed." (PMID 27311570, 2016). "Many studies have shown that PTK6 play different roles in normal and cancer epithelia, suggesting that the function of PTK6 may associate with its intracellular localization (cytosol or nuclei)." (PMID 23758975, 2013). "One such cancer-associated PTK is breast tumor kinase/protein tyrosine kinase 6 (Brk/PTK6)." (PMID 21923922, 2011). "Research indicates that PTK6 is often overexpressed in cancers like breast and colon, significantly contributing to cell growth and survival by affecting key signaling pathways." (PMID 40510341, 2025). "assessed the prognostic significance of PTK6 expression in cancer tissues, emphasizing its predictive role across different cancers, with prognostic implications affected by PTK6 levels in adjacent non-cancerous tissues." (PMID 40809015, 2025). "Further methylation analysis demonstrates a decrease in PTK6 promoter methylation levels in pan-cancer, aligning with our previous expression studies." (PMID 38573548, 2024). "PTK6 has been studied in various cancers, however, the roles of PTK6 on LUAD progression remain controversial." (PMID 38573548, 2024). "The findings of our study indicate that PTK6 mRNA and protein levels exhibit significant upregulation across various cancer types." (PMID 38573548, 2024). "In this study, we focus on the level of PTK6 expression and its relationship with immunity in pan-cancer, especially in LUAD." (PMID 38573548, 2024). "Afterwards, the correlation between different immune subtypes and PTK6 expression in pan-cancer were examined." (PMID 38573548, 2024). "This study employs bioinformatics and experimental methods to conduct a comprehensive investigation into the involvement of PTK6 in cancer." (PMID 38573548, 2024).
cancer (continued). "It thus has important prognostic value in this cancer type.Results obtained recentlyusingmouse models have shown that PTK6 promotes cell survival, delays degeneration, and favors tumor formation by inducing a P38-driven pro-survival signaling pathway." (PMID 37932734, 2023). "These authors also found that PTK6 promoted the development and metastasis of cancer by increasing STAT3 phosphorylation and ZEB1 expression." (PMID 37932734, 2023). "Despite the growing evidence of PTK6’s oncogenic function in cancers, there have been few conclusive studies on the clinical benefits of targeted PTK6 inhibitors." (PMID 37509364, 2023). "In TNBC cell models, it was found that PTK6 mediated cancer phenotypes via the AhR and ras homolog gene family, member A (RhoA) activation." (PMID 36831661, 2023). "Results of further gene-level analysis revealed that the SCNAs of known cancer-related genes, such as PTK6 (44.6%), ERBB3 (13.4%), PIK3CA (11.8%), and UBR5 (11.8%), were relatively frequent (eFigure 4 in Supplement 1)." (PMID 36484990, 2022). "Based on datasets from the TCGA database and GTEx database, we studied the expressions and functions of PTK6 across 33 different kinds of cancer." (PMID 36405012, 2022). "PTK6 has been proven to have significant cancer-promoting effects in a number of different cancer types." (PMID 36405012, 2022). "PTK6 is highly expressed and activated in multiple cancer types, including breast, prostate, pancreatic, and oral cancers." (PMID 35562900, 2022). "Stable knockdown of PTK6 in multiple cancer cell lines leads to decreased activating phosphorylation of SRC." (PMID 36228719, 2022). "Over the past few years, a number of studies have demonstrated that PTK6 was dysregulated in a variety of cancers." (PMID 36405012, 2022). "Cytoplasmic PTK6 can interact with over 30 identified substrates within the cytosol and participate in facilitating oncogenic functions of cancer cells to enhance their migration and invasion." (PMID 34340703, 2021). "In contrast, PTK6 has been shown to be overexpressed in multiple cancer types as an oncogene and to be localized in the cytoplasm and at the cell membrane." (PMID 34340703, 2021). "One of the clearest signals of selection is on PTK6, a tyrosine-protein kinase involved in several cancer pathways." (PMID 33185667, 2021). "We found that validated genes are involved in pathways like focal adhesion, PTK6 expression, muscle contraction and proteoglycans in cancer." (PMID 33731721, 2021). "We also found significant enrichment for known cancer driver genes from the COSMIC (Catalogue Of Somatic Mutations In Cancer) database in our predicted causal genes list, such as CDK4, EGFR, PTK6, and CCND1 (29/264; Fisher adjusted p < 0.01)." (PMID 34010657, 2021). "Increased PTK6 expression is found in PCa, especially at metastatic stages, and in other cancer types such as lung, bladder, ovarian, cervical, pancreas, gastric, head and neck cancers, and B- and T-cell lymphomas." (PMID 31278310, 2019). "Increased expression and an oncogenic role of PTK6 has been shown in multiple cancers including PCa33,34,57,58." (PMID 31278310, 2019). "Both kinase-dependent and -independent functions of PTK6 in driving tumor growth have been described, therefore targeting PTK6 kinase activity by small molecule inhibitors as a therapeutic approach to treat cancers remains to be validated." (PMID 29879184, 2018). "PTK6 promotes cancer cell proliferation, migration and survival through activating oncogenic signalling pathways." (PMID 27713912, 2016). "Due to its overexpression in various cancers, more and more studies have tried to uncover the role of PTK6 in the biological behavior of cancers." (PMID 25748447, 2015). "Although there is an accumulating evidence that PTK6 is aberrantly expressed in various epithelial cancers, the implication of PTK6 expression and its role in the biological behavior of cancers are controversial and poorly defined." (PMID 24788754, 2014).
cancer (continued). "Activation of PTK6 at the cell membrane highlights the need for development of strategies to target membrane specific functions of PTK6 in cancer." (PMID 25153721, 2014). "These apparently opposite reports about the influence of of PTK6 on cancer biology highlight the importance of studies investigating the effects of individual signals in individual types of cancers." (PMID 24788754, 2014). "Fully understanding functions of ALT-PTK6 and its impact on PTK6 signaling will be critical for development of therapeutic strategies that target PTK6 in cancer." (PMID 21479203, 2011). "Additionally, epigenetic modifications, including amplified factors such as RUVBL1 and protein tyrosine kinase 6 (PTK6), play pivotal roles in driving cancer proliferation and influencing immunotherapy responses." (PMID 41244916, 2025). "Therefore, the objective of our study was to assess the promoter methylation status of PTK6 across a range of cancer types." (PMID 38573548, 2024). "However, in cancers such as breast and ovarian, PTK6 is involved in cellular proliferation, migration, and survival activities." (PMID 37509364, 2023). "Given that STK11/LKB1, CDKN2A, and PTK6 each have well-described roles in cancer progression, we hypothesized that PAQR8 might play a role in breast cancer recurrence." (PMID 36597146, 2023). "The cancer tissues of all TNBC patients were examined for PTK6 expression using IHC technique." (PMID 37932734, 2023). "Since it has been shown that LINK-A controls HIF-1α stabilization through interaction with PTK6 and LRRK2 in cancer cells, this prompted us to evaluate whether PTK6 and LRRK2 mediate increased LINK-A–induced HIF-1α expression in RA FLSs." (PMID 34877935, 2021). "Moreover, several pathways were significantly enriched by this gene expression profile such as focal adhesion, PTK6 expression, muscle contraction and proteoglycans in cancer." (PMID 33731721, 2021). "The aberrant expression of PTK6 has been identified in a variety of epithelial tumors including breast, colon, non-small cell lung, pancreatic, prostate, ovarian and gastric cancer." (PMID 34551797, 2021). "In line with our findings, PTK6 promotes cancer cell aggressiveness." (PMID 34877935, 2021). "Thus, PSPC1 is the contextual determinant of the oncogenic switch of PTK6/β-catenin subcellular localizations, and PSPC1-CT131 functions as a dual inhibitor of PSPC1 and PTK6 with potential for improving cancer therapy." (PMID 31844057, 2019). "In conclusion, C/EBPα might attenuate Wnt/β-catenin signaling and impact on cancer cell proliferation by controlling expression of Ptk6." (PMID 30599048, 2019). "We also demonstrated that PSPC1-CT131 is a dual pharmacologically inhibitor targeting oncogenic PSPC1 and PTK6 and might be an advanced avenue for exploring clinical interventions to prolong survival of cancer patients." (PMID 31844057, 2019). "The function of PTK6 in normal epithelia and in cancer is not fully understood." (PMID 27311570, 2016). "PTK6 impacts survival of both normal and cancer cells, and may seemingly play contradictory roles in these two contexts." (PMID 26084280, 2015). "It has been reported that PTK6-promoted cancer migration occurs through ERK signaling, thus, we sought to determine whether ERK signaling also played a role in S1P-triggered migration." (PMID 25748447, 2015). "Understanding the kinomic differences between cancers in which PTK6 promotes migration and those in which it inhibits migration may be a fruitful subject for future study." (PMID 24788754, 2014). "In addition, PTK6 confers cancer cell resistance to anoikis and knockdown of PTK6 increases sensitivity of cancer cells to different therapeutic agents." (PMID 25153721, 2014). "However, PTK6 also participates in cancer progression by sensitizing cells to mitogenic signals, enhancing proliferation, migration/invasion, and anchorage-independent survival in tumor tissues." (PMID 23758975, 2013).